ABCC6P1 (ATP binding cassette subfamily C member 6 pseudogene 1)
Gene: Transcribed unprocessed pseudogene on chromosome 16 (18,571,276 to 18,592,716, forward strand). Ensembl gene ENSG00000256340.
Diseases named in the same sentence as ABCC6P1 in open-access papers:
ABCC6P1 is named in the same sentence as 5 diseases in open-access papers, as found by Europe PMC text mining. Sharing a sentence is not in itself a finding about the gene and the disease. The quoted sentences say what the papers report.
chordoma (1 paper, 2020). Chordomas are rare malignant tumors arising from embryonic remnants of the notochord in axial skeleton. "The EGF mRNA and lncRNA AL078621.4 were down-regulated, while lncRNA ABCC6P1 was up-regulated in no dural penetration chordoma samples." (PMID 32533822, 2020). "Next, we analyzed the expression of EGF mRNA and the lncRNAs ABCC6P1 and AL078621.4 located in the lncRNA-mRNA co-expression network to explore whether EGF was regulated by these differentially expressed lncRNAs in dural penetration chordoma." (PMID 32533822, 2020). "Additionally, mRNA for EGF and its regulatory lncRNAs levels of ABCC6P1 and AL078621.4 in chordoma tissues with serious dural penetration or without dural penetration were detected by RT-qPCR." (PMID 32533822, 2020).
hepatoma (1 paper, 2008). "-233 bp), known to confer high-level ABCC6 expression in HepG2 hepatoma cells, is completely conserved in the putative ABCC6P1 promoter region." (PMID 18405356, 2008).
Pseudoxanthoma elasticum (1 paper, 2008). "Knowledge of ABCC6/ABCC6P1 regulatory interaction may be of potential relevance to clinical medicine because ABCC6 is the underlying gene defect in the syndrome pseudoxanthoma elasticum." (PMID 18405356, 2008). "Two pseudogenes, ABCC6P1 and ABCC6P2, have been reported for the pseudoxanthoma elasticum gene ABCC6, a member of the ABC C-subfamily." (PMID 18405356, 2008).
tumor (1 paper, 2018). "Compared with paired normal thyroid tissues, four lncRNAs (LOC100130238, HAND2‐AS1, MIR9‐3HG, and LOC143666) were downregulated in PTC tumor tissues, whereas the remaining four lncRNAs (EGFEM1P, LINC00284, TINCR, and ABCC6P1) were upregulated in PTC tumor tissues." (PMID 30318850, 2018).
ABCC6P1 also shares sentences with these, for which no sentence is quoted: breast carcinoma (1 paper).